PLK1 (polo like kinase 1)
Diseases named in the same sentence as PLK1 in open-access papers (continued):
Sharing a sentence is not in itself a finding about the gene and the disease.
cancer (continued). "This study further establishes the theoretical foundation of the specific NM‐protein interaction, uncovers the molecular basis of specific targeting of PLK1 by BPNMs, and enhances their potential as specific PLK1 inhibitors in cancer chemotherapy." (PMID 41476654, 2025). "To address these issues, we considered Proteolysis Targeting Chimeras (PROTACs) as a promising tool to degrade PLK1 in cancer cells." (PMID 40871048, 2025). "Some studies have suggested that the high selectivity of PLK1 inhibitors for the BET bromodomain is the reason why PLK1 inhibitors can be used as drug targets for cancer and inflammation." (PMID 40612941, 2025). "Different studies have shown that inhibiting PLK1 using RNAi or small molecule inhibitors interferes with cancer cell proliferation and this has fostered the development of PLK1 inhibitors (PLK1is) as new anti-cancer drugs." (PMID 39859203, 2025). "HER2-enriched cancers involved four regulators of PLK1 activity at G2/M transition in the cell cycle, CEP63, CEP250, NEDD1, and HAUS3." (PMID 40700427, 2025). "Polo-like kinase 1 (PLK1) is a major regulator of cell division and has been pursued as a drug target for cancer therapy for a long time." (PMID 41246821, 2025). "To this end, we selected 210 single guide RNA (sgRNA) sequences targeting 105 genes and queried their relevance in PLK1-overexpressing cancer by using in vivo pooled and in vitro arrayed CRISPR screens." (PMID 40347943, 2025). "The findings from this study established that PLK1 is not only recognized as a critical multi-target oncogene but also as a viable target for cancer diagnostics and therapeutics." (PMID 41404416, 2025). "The development of B4-like PLK1 inhibitors has the potential to address the unmet medical need in cancer treatment." (PMID 40355412, 2025). "Overall, these in vitro analyses support the potential for IGF2BP2 inhibition in the selective elimination of PLK1-overexpressing cancer cells." (PMID 40347943, 2025). "It elucidated the mechanism by which BPNMs act as an effective PLK1 inhibitor for cancer chemotherapy and offered a practical solution for targeted cancer treatment using myeloid cell membrane‐coated BPNMs." (PMID 41476654, 2025). "Given the overexpression features of PLK1 in tumors and its potential role in chemoresistance, targeting PLK1 pathway is an attractive strategy for overcoming drug resistance in cancer treatment." (PMID 40355412, 2025). "The detailed SAR studies finally led to the six most potent compounds 29–34 having > tenfold higher inhibitory activity of Plk1 PBD than that of PLHSpT, which offer some potential lead compounds for future drug discovery against Plk1-addicted cancers." (PMID 40141117, 2025). "It has been shown that CIP2A and PLK1 interact directly to facilitate spindle assembly and modulate cell cycle progression in cancer cells." (PMID 39657788, 2025). "As a result, numerous studies have demonstrated the potential of PLK1 as a potent target for cancer treatment, and clinical trials are currently underway to validate the efficacy and safety profiles of PLK1 inhibitors." (PMID 41284701, 2025). "The obtained results indicate that plk1 dysregulation has profound effects on chromosomal stability and correlates with reduced patient survival across multiple cancer types." (PMID 40430225, 2025). "In recent years, tremendous advances in understanding the regulatory mechanisms by which PLK1, a key mitotic kinase extensively investigated as a cancer drug target, have been achieved." (PMID 40379873, 2025). "Targeting PLK1 to reverse its oncogenic role in cancer cells is a promising anticancer strategy for inducing apoptosis." (PMID 40871048, 2025). "PLK1's oncogenic effects extend beyond its mitotic functions; it phosphorylates multiple cancer‐relevant substrates, promoting cell survival and metastasis." (PMID 40370109, 2025).
cancer (continued). "For example, PLK1 is markedly expressed in a multitude of malignant neoplasms, particularly in LC, and has the capacity to facilitate tumor development through classical pathways such as the PI3K-AKT, NF-κB, and MAPK pathways." (PMID 41460629, 2025). "PLK1 plays an important role in the cell cycle, and many studies have reported that inhibition of PLK1 induces apoptosis of cancer cells by arresting in the mitotic phase." (PMID 39809780, 2025). "Recent studies have suggested that PLK1 regulates the motility and invasiveness of several cancer cells." (PMID 38355643, 2024). "PLK1 is often elevated in a wide variety of human cancers compared to normal tissues, giving these cancer cells a growth and invasion advantage." (PMID 39085197, 2024). "These pathways encompassed the plk1 pathway, retinoblastoma gene in cancer, cell cycle checkpoints, resolution of sister chromatid cohesion, activation of atr in response to replication stress, aurora b pathway, G2 M checkpoints, and atr pathway." (PMID 38601162, 2024). "PLK1 inhibition has been shown to exhibit anti-tumoral activity by blocking mitosis in cells with higher PLK1 expression, making it an attractive target for cancer therapy." (PMID 39057065, 2024). "The filtered blue module (203 genes) contained several genes associated with various typesof cancers and cell cycle regulation, including TTK, PLK1, LRG1, and CDK1." (PMID 39439565, 2024). "Accordingly, inhibiting PLK-1 expression has been observed to significantly reduce cell proliferation and induce apoptosis in various cancer cells." (PMID 39857637, 2024). "The present study established a novel mechanism by which PLK1 regulates the migration and invasion of cancer cells." (PMID 38355643, 2024). "Similar observations have been reported for other genes such as CXCL11, Plk1, and CD177, where high expression levels are unexpectedly associated with better clinical outcomes in specific cancer types." (PMID 38890197, 2024). "Regarding the tumor‐promoting role of PLK1 in cancer, significant effort has been made to inhibit this factor." (PMID 38919334, 2024). "PLK1 inhibitors, in combination with chemotherapy, have shown enhanced anti-cancer efficacy both in vitro and in vivo by leveraging complementary mechanisms, leading to stronger tumor suppression." (PMID 39451218, 2024). "Aberrant overexpression of PLK1 has been observed in many cancer types and often correlates with poor prognosis." (PMID 38780513, 2024). "PLK1 is typically expressed at low levels in healthy tissues but is found to be highly expressed in various types of cancer, such as breast and gastric cancer." (PMID 38393054, 2024). "Polo-like kinase 1 (PLK1) is a crucial mitotic kinase that is frequently overexpressed in numerous cancers, where it facilitates carcinogenesis and accelerates disease progression." (PMID 39596658, 2024). "MYC and PLK1 are major drivers of tumorigenesis, enhancing cancer cell growth and proliferation via autophagy and increased PLK1 levels are associated with poor cancer prognosis." (PMID 37450923, 2024). "Overexpression of AURKA/B, CDK1, and PLK1 has been reported in several malignant tumors, including HCC." (PMID 38672246, 2024). "Disrupting PLK1 through knockout has been observed to reduce cancer cell survival, trigger apoptosis, and enhance sensitivity to chemotherapy drugs, with minimal impact on normal cells." (PMID 38886738, 2024). "PLK1 inhibitors have shown promise as potential cancer drugs due to their role in regulating mitotic events and the proliferative activity of cancer cells." (PMID 38201308, 2024). "The proliferative signature of cancer cells is known to be causally linked to expression of a core set of pro‐proliferative genes including MYBL2, BUB1, and polo‐like kinase 1 (PLK1)." (PMID 38538106, 2024).
cancer (continued). "Overexpression of PLK1 has been observed in various cancers including lung cancer, where it promotes metastasis through mechanisms that are not fully understood." (PMID 38780513, 2024). "Genomics of Drug Sensitivity in Cancer (GDSC) and Cancer Therapeutics Response Portal (CTRP) analysis revealed MC hub/prognostic genes show highest sensitivity towards two compounds - BI-2536 (PLK1 inhibitor) and AR-42 (histone deacetylase (HDAC) inhibitor)." (PMID 39015573, 2024). "Collectively, we demonstrate that the phosphorylation of RhoGDI1 by PLK1 promotes cancer cell migration and invasion through RhoA activation." (PMID 38355643, 2024). "These nanocarriers successfully downregulate polo‐like kinase 1 (PLK1) expression to suppress cancer progression." (PMID 38919334, 2024). "PLK1 is an attractive target for overcoming chemoresistance and immune checkpoints in clinical cancer therapy." (PMID 39353904, 2024). "PLK1 activation is responsible for cancer progression and drug resistance, while its downregulation exerts antiproliferative effects." (PMID 38919334, 2024). "In particular, APE1 promotes YBX1 dual-phosphorylation at S174 and S176 by modulating PPP1R12A and PLK1 to enhance SG formation and cancer cell survival." (PMID 38436697, 2024). "In the current study, we identified PLK1 as a novel kinase of RhoGDI1 and provided new mechanistic insight into the regulation by PLK1 of cancer cell migration and invasion via RhoA activation." (PMID 38355643, 2024). "Inhibition of PLK1 disrupts the maintenance of stemness in cancer cells, thereby suppressing the stem cell-like traits that contribute to tumorigenesis, therapeutic resistance, and disease progression." (PMID 39451218, 2024). "The multifaceted effects of PLK1 inhibition in cancer treatment prompted us to explore the downstream effectors involved." (PMID 39451218, 2024). "For instance, it has been demonstrated that the expression of PLK-1 in cancer tissue is substantially higher than in normal colorectal tissue." (PMID 39857637, 2024). "Regarding cancer proliferation and invasion-associated markers, Ki67, MMP2, and MMP9 protein levels were significantly decreased following PLK1 knockdown relative to the si-NC group." (PMID 39524172, 2024). "It seems that the suppression of Plk1 expression can promote cancer cell apoptosis and prevent tumor development." (PMID 38951806, 2024). "PLK1 is found to be highly expressed in various types of cancers, but the development of inhibitors for it has been slow." (PMID 38393054, 2024). "Another important aspect, based on clinical data from PLK1 inhibitors explored as monotherapies in cancer patients, is the limited therapeutic effects reported in patients with solid tumors due to dose-limiting toxicities." (PMID 39184047, 2024). "Dysregulation of PLK1, characterized by heightened expression levels, has been identified as a pivotal player in the initiation and progression of various cancer types." (PMID 38885192, 2024). "Polo-like kinase 1 (PLK1) is a valuable target in cancer treatment due to its prognostic implications and clinical relevance." (PMID 38791595, 2024). "Dual TTK/PLK1 inhibition represents a novel approach for the treatment of human cancer, including TNBC patients, with a potential for potent anticancer activity and a favorable therapeutic index." (PMID 39184047, 2024). "PLK1 is a crucial molecule for cell cycle regulation that promotes tumor proliferation in several cancer types." (PMID 38057358, 2024).
cancer (continued). "Recently, PLK-1 was described as one driver in infant MLLr leukemogenesis and maintenance, but it is also found in a variety of human cancers with poor prognosis." (PMID 39684470, 2024). "Blocking the expression of PLK1 can result in the death of cancer cells by disrupting various phases of cell division, making PLK1 a promising candidate for cancer treatment." (PMID 39628476, 2024). "In other cancer cell types, PLK-1 inhibition has been shown to amplify the effects of radiation therapy, which induces double-stranded DNA breaks (DSBs) and activates DNA repair pathways." (PMID 38540116, 2024). "The results demonstrated that HSP90AA1 was enriched in cancer pathways such as the Hippo pathway, PLK1 pathway, PI3K/AKT pathway and WNT pathway." (PMID 39567496, 2024). "PLK1 also regulates the migration and invasion of various cancer cell lines, including colorectal, prostate, and lung cancer cells." (PMID 38355643, 2024). "A number of TTK and PLK1 inhibitors have entered clinical development for the treatment of cancer, with the TTK inhibitors mainly explored in combination with taxanes and more recently with estrogen receptor (ER) antagonists." (PMID 39184047, 2024). "For example, BI-2536 was used in the treatment of various cancers by perturbing the cell cycle through PLK1/2/3." (PMID 39796714, 2024). "Integrated bioinformatics analyses and functional investigation have identified PLK1 as a promising therapeutic target in various cancer types, including SCLC." (PMID 39085197, 2024). "Given PLK1’s functional role in cell cycling throughout tumor progression, researchers have investigated PLK1 inhibitors in numerous clinical trials as potential therapeutic agents for cancer patients." (PMID 38886738, 2024). "Combination therapy of lapatinib with inhibitors targeting either PAI1 or PLK1, eliminated fibroblast-protected cancer cells, under both conditions of direct coculture with fibroblasts and protection by fibroblast-conditioned medium." (PMID 39513002, 2024). "Next, IPA was used to understand the cumulative actions of genes identified in response to PLK1 inhibition, and this analysis predicted the inhibition of migration of cancer cells." (PMID 38184733, 2024). "All cancer cell lines exhibited a dose-dependent reduction in the number of viable cells after four days of PLK1 pharmacologic blockade." (PMID 39513002, 2024). "The PLK1 plays a crucial role in regulating cellular mitosis, and is highly expressed many types of cancers, including LUAD." (PMID 38345559, 2024). "Emerging research has revealed the frequent overexpression of PLK1 in various cancer types, which correlates with unfavorable prognostic outcomes, rendering it an appealing candidate for cancer treatment." (PMID 38560572, 2024). "These inhibitors target the kinase domain of PLK1 and prevent its enzymatic activity, leading to disrupted cell division and apoptosis in cancer cells." (PMID 38780513, 2024). "Studies have confirmed that PLK1, a kind of serine/threonine-protein kinase, is overexpressed and play an oncogenic role in various types of cancer." (PMID 38414025, 2024). "Among the different strategies applied to reverse chemoresistance, the use of shRNA has been considered, since this genetic tool can downregulate expression of genes like WT1, AMBRA1, Bcl‐xL, and PLK1 to eventually enhance the chemosensitivity of cancer cells." (PMID 38919334, 2024). "We next treated all five cancer cell lines cultured with fibroblasts to assess how direct coculture with fibroblasts affects cancer cell response to lapatinib plus PLK1 inhibition." (PMID 39513002, 2024). "Cumulatively, these data supported the conclusion that PLK1 also regulated MHC-II in LUAD cancer cells." (PMID 38885192, 2024). "In this study, 3D-QSAR, molecular docking, and molecular dynamics (MD) simulations were applied on a series of novel pteridinone derivatives as PLK1 inhibitors to discover anti-cancer drug candidates." (PMID 36676076, 2023).
cancer (continued). "Gain/loss-of-function assays, cell viability assay, xenograft models, and IHC staining were conducted to evaluate the anti-cancer effects of co-inhibition of ST8SIA6-AS1/PLK1 pathway and KRAS both in vitro and in vivo." (PMID 38104151, 2023). "Both poloxin and thymoquinone can obstruct the correct orientation of PLK1, effectively impeding the mitosis of cancer cells." (PMID 37958623, 2023). "As cancer cells often overexpress PLK1 and are hypersensitive to PLK1 inhibition, PLK1 represents a cancer-cell specific vulnerability." (PMID 37639469, 2023). "Nowadays, many Plk1-related anti-cancer drugs are able to effectively kill tumor cells, but their unwanted toxicity to normal cells still restricts their clinical application." (PMID 36845678, 2023). "By inducing the phosphorylation of substrates, PLK1 plays critical roles in various types of diseases including cancer." (PMID 37788997, 2023). "The data described in the present study showed that the combined inhibition UBE2C and PLK1 or BIRC5 caused a decrease in the mRNA expression of ACLY, suggesting a possible novel strategy for cancer therapy." (PMID 37958642, 2023). "Overall, targeting both BRD4 and PLK1 represents a promising strategy for developing novel anticancer therapies, because this dual inhibitor can inhibit multiple processes involving cancer growth and survival." (PMID 37765111, 2023). "The present study demonstrated the inhibitory nature of PtB against the PLK-1 protein, establishing its potential usefulness as a small molecule inhibitor for the treatment of different types of cancer." (PMID 37570823, 2023). "Despite the limited efficacy of phase II trials in NSCLC patients, PLK1 is considered a synthetic lethal target in KRAS-mutant cancers, which are proved to be sensitive to mitotic perturbations and hypersensitive to the PLK1 suppression." (PMID 38104151, 2023). "Given its prominent role in cell cycle progression, the overexpression of PLK1 is considered a cancer driver by overriding cellular checkpoints and inducing genetic instability." (PMID 37958642, 2023). "Since the reversal of an addicted state is considered an effective strategy to selectively suppress cancer cell proliferation (6, –8), antagonizing Plk1 function has been considered an attractive approach to combat Plk1-addicted cancers." (PMID 37603740, 2023). "The phosphorylated FoxM1 at Ser25 by PLK1 acquires the reprogramming ability to stimulate the invasive traits in cancer and influence immune cell plasticity." (PMID 37968723, 2023). "This challenge spurred the development of more refined PLK1 inhibitors, strategically designed to selectively target cancer cells." (PMID 37988371, 2023). "Given PLK1’s well-established role as an oncogene across various cancer types, our sustained interest has been drawn to the potential of targeting PLK1 for cancer therapy." (PMID 37988371, 2023). "Inhibitors of WEE1, ATR, CHK1 and PLK1 have also achieved preliminary response in certain types of cancer patients." (PMID 37679326, 2023). "One potential strategy to overcome these limitations is co-treatment with other drugs that specifically sensitize cancer cells to partial PLK1 inhibition." (PMID 37639469, 2023). "Polo-like kinase 1 (PLK1), a key mitotic regulator, is frequently overexpressed in multiple human cancers." (PMID 37958442, 2023). "PLK1 is upregulated in many cancer types, and PLK1 inhibitors have been actively pursued as an anticancer therapy." (PMID 36626982, 2023). "Owing to the critical role of PLK1 in human cancers, there has been significant interest in developing PLK1 inhibitors since the early 2000s." (PMID 37174744, 2023).